PARP2 (poly(ADP-ribose) polymerase 2)
Diseases named in the same sentence as PARP2 in open-access papers (continued):
Sharing a sentence is not in itself a finding about the gene and the disease.
cancer (continued). "Inhibitors of tankyrases (the selective inhibitor STP1002 and the dual PARP1/PARP2 and TNKS1/TNKS2 inhibitor E7449), PARP7 (RBN-2397), and PARP14 (RBN-31430) are currently undergoing clinical trials for treatment of cancer and inflammatory diseases." (PMID 37832523, 2023). "As known, PARPis can restrain DNA repair and induce the apoptosis of cancer cells by inhibiting PARP, with most functions performed by PARP-1 (85%–90%) and PARP-2 (10%–15%)." (PMID 36923428, 2023). "PARP suppressors affect PARP1 and PARP2, blunt BER, and sensitize malignant cells to temozolomide, constituting potential combinatory agents for use with temozolomide in cancer." (PMID 35422863, 2022). "The GDSC data set had a total of 47 unique drugs with ten targets, including EGFR, IGF1R, HDAC1, PARP2, AURKA, and BRAF, as well as their sensitivities across 224 cancer cell lines." (PMID 33795761, 2021). "As far as the inducible increases of PARP2/ACTB mRNA ratios are concerned, ASA-A, ASA-B and POPA were comparably more effective, whereas ASA-C was less effective against all tested cancer cell lines." (PMID 34440232, 2021). "In general, the results indicated that the PARP1/ACTB and PARP2/ACTB mRNA cellular content ratios are notably increased (t-test, p < 0.001) in most cases and for all tested cancer cell lines after treatment with the alkylators ASA-A, ASA-B, ASA-C and POPA." (PMID 34440232, 2021). "Chromatin immunoprecipitation (ChIP) assay showed that PARP2 bound to CCL3 proximal promoter in both IMCs and cancer cells." (PMID 32221289, 2020). "To determine the effect of PARP deletion in the entire cancer environment on bone metastasis, we examined PARP1 or PARP2 global knockout (KO) mice." (PMID 32221289, 2020). "Chromatid scattering was observed in various cancer cell lines and was correlated with PARP1 and PARP2 expression levels." (PMID 29262611, 2017). "Primarily, targeting only PARP1, and not PARP2, is sufficient for efficacy in HRR-deficient cancer cells." (PMID 41459749, 2025). "Collectively, these studies may encourage the development of therapeutic approaches differentially targeting PARP1 and PARP2, especially in ALT cancers and more generally in cancer cells harboring high levels of replication stress." (PMID 38565848, 2024). "Our findings point towards a role for PARP2 in the repair of collapsed replication forks during replication stress and highlight the significance of developing PARP-specific inhibitors for effective cancer treatment." (PMID 38565848, 2024). "Additionally, anti-cancer therapeutics targeting PARP1 and PARP2 have been developed and are currently widely used in clinics." (PMID 36814782, 2023). "In addition to ADP-ribosylation systems implicated in bacterial or viral infections, the primary connection between ADP-ribosylation and human health comes from sensitivity of some cancer phenotypes to the inhibition of PARP1 and PARP2." (PMID 37832523, 2023). "Rucaparib (RCP) is a potent selective inhibitor of both PARP-1 and PARP-2, which induces synthetic lethality in cancer cells that are not able to repair DNA damage by the HRR pathway." (PMID 35236893, 2022). "Some mitomiRs specifically regulate mitochondrial metabolism (mir-149 controls PARP2 and SIRT1 expression, mir-326 regulates PKM2 expression in cancer cells, mir-25 controls Ca uptake and ROS production, and mir-128a regulates BMI-1 expression to ensure redox homeostasis)." (PMID 36496979, 2022). "Consequently, as was revealed, the more sensitive a cancer cell line to the cytostatic and cytotoxic effects of a tested compound, the higher the increase of the relative PARP1/ACTB and PARP2/ACTB mRNA ratios observed." (PMID 34440232, 2021). "In addition, these compounds promoted a more appreciable elevation of the PARP2 mRNA transcription in the BRCA1-null UWB1.289 than BRCA1 wild-type, UWB1.289 + BRCA1 cancer cells." (PMID 34440232, 2021).
cancer (continued). "ASA-A, ASA-B and POPA brought about a considerably higher increase of the PARP2/ACTB mRNA ratio in the BRCA1-null UWB1.289 than in the BRCA1 wild-type UWB1.289 + BRCA1 cancer cells, with the ASA-B begetting a 140- to150-fold increase of the PARP2/ACTB mRNA ratio in UWB1.289 cells." (PMID 34440232, 2021). "Drugs with targets such as EGFR, ERBB2, MTOR, PARP2, AURKB, MAP2K1 and PLK1 share more similar profiles, which indicates that the inhibition of these targets has specific effects on the in vitro viability and proliferation of cancer cells." (PMID 33795761, 2021). "In addition, we have shown that in the physiological state there is a positive relationship between PARP1, PARP2, and TRPM2, which is disturbed in cancer cells." (PMID 32423430, 2020). "Across progression trajectories, our results show that expression of genes related to ADP‐ribosylation decreased as tumors progressed (while PARP1 and PARP2 increased or remained stable), suggesting the potential for a differential response to PARP inhibitors based on cancer progression." (PMID 32207233, 2020). "To delineate which cell type in the myeloid lineage, other than osteoclasts, confers the differential regulation of bone metastasis by PARP1 and PARP2, we performed flow cytometry analyses (FACS) of bone marrow cells isolated from mice receiving cancer cells via intracardiac injection." (PMID 32221289, 2020). "Emerging evidence supporting the immunomodulatory roles of PARP-1 and PARP-2 has raised the prospect of harnessing PARP inhibition to not only target the cancer itself, but also therapeutically modify its microenvironment." (PMID 32046278, 2020). "ChIP assay showed that β-catenin binding at CCL3 promoter was significantly augmented by the KD of PARP2 but not by PARP1 in cancer cells." (PMID 32221289, 2020). "On the other hand, we found PARP2 highly correlated with zinc fingers C2H2-type genes (ZNF) in normal but not cancer tissue." (PMID 30532070, 2019). "Olaparib-induced mitotic chromatid scattering was observed in various cancer cell lines with increased protein levels of PARP1 and PARP2, but not in non-cancer or cancer cell lines that expressed lower levels of PARP1 or PARP2." (PMID 29262611, 2017). "Poly(ADP-ribose) polymerase inhibitors (PARPIs) kill cancer cells by trapping PARP1 and PARP2." (PMID 27708213, 2016). "It was also hoped that a global view of the PARP-1, PARP-2 and PARG interactomes may help to grasp the ramifications of cancer treatment by PARP inhibitors, either in terms of therapeutic efficiency or side effects." (PMID 20388209, 2010). "Furthermore, synthetic lethality in BRCA-mutated cancers depends mostly on PARP1, whereas PARP2 is not essential." (PMID 40521389, 2025). "Consequently, PARP2 does not play a role in the efficacy of olaparib and veliparib in BRCA1m cancer cells, it is entirely PARP1-dependent." (PMID 41459749, 2025). "Similar to PARP2, not much is known about the potential role of PARP3 in cancer cell death resistance apart from a study that reported poor prognosis of patients with PARP3 overexpressing breast cancers who received chemotherapy." (PMID 33922595, 2021). "However, in contrast to other cancers, we did not observe MYC-mediated transcriptional activation of DDR genes such as CHK1, PARP1, PARP2, and BRCA144–46." (PMID 31266951, 2019).
tumor (60 papers, 2013 to 2026). "For example, Niraparib is a selective PARP-1 and PARP-2 inhibitor with favorable pharmacokinetics and anti-tumor roles in patients with BRCA1/2 mutations." (PMID 39588300, 2024). "Single PARP2-deficiency was shown to inhibit tumour progression while dual PARP1/PARP2-deficiency promotes tumour growth in T cells." (PMID 37667522, 2023). "PARPs are readily druggable and PARP inhibitors (PARPi) against the main DDR-associated PARPs, PARP1 and PARP2, are currently approved for the treatment of a range of tumor types." (PMID 36533080, 2022). "The double deficiency of PARP-1/PARP-2 reduces the number of infiltrating T and NK cells in the microenvironment, creating an environment conducive to tumor growth." (PMID 35906622, 2022). "A reduction in tumor growth in PARP2-deficient host-mice, compared to wild-type specimens (C57 and Balb/c) has also been associated with the immunomodulatory role of PARP2." (PMID 34445986, 2021). "Accordingly, T cell lymphopenia in dual PARP-1/PARP-2-deficient mice can affect the recruitment of lymphocytes to the tumor microenvironment." (PMID 32046278, 2020). "Interestingly, single and double PARP-1 and PARP-2 deficiency play opposite roles in the tumor microenvironment." (PMID 35906622, 2022). "PARP-2 deficiency in the tumor leads to increased RANKL and decreased osteoprotegerin expression." (PMID 33923319, 2021). "Moreover, nobiletin inhibited the expression of poly(ADP‐ribose)polymerase‐2 (PARP‐2), and the tumor suppression effect of nobiletin on C666‐1 is associated with PARP‐2‐dependent pathway." (PMID 30918653, 2019). "Moreover, a defect in the ability of dually PARP-1/PARP-2-deficient T cells to differentiate into effector cells could have consequences for the anti-tumor response." (PMID 32046278, 2020). "Specifically, PARP1 and PARP2 expression were higher in MSI more than MSS tumours, and in Hypermutated more than either chromosomal instability (CIN)/Epithelial or genome-stable (GS)/Mesenchymal tumours." (PMID 40573300, 2025). "In TNBC, selective degradation of PARP-2 using a proteolysis-targeting chimera (PROTAC) showed significant anti-tumour effects in both cell lines and xenograft models." (PMID 39201718, 2024). "In another investigation, a reduction in tumor burden was observed in mice that were genetically deficient for PARP-1 and PARP-2 expression and activity through increased oxidative stress." (PMID 36768904, 2023). "PARP1 and PARP2 have distinct roles and mechanisms in tumour development, despite sharing a similar catalytic domain." (PMID 37667522, 2023). "PARP1 and PARP2 transcript levels were significantly higher in tumor than all peri-tumor and control tissues except NASH-associated tumors." (PMID 35804391, 2022). "PARP1 and PARP2 transcript levels were significantly higher in Tumor than Peri-Tumor and control tissues with PARG transcripts higher in all except NASH-associated Tumor tissues." (PMID 35804458, 2022). "Tumor subtype analyses of LoF variants revealed evidence of association for ZFAND1, TYRO3, DNAH11, and PARP2 with ER-negative breast cancer, with ZFAND1 showing the strongest association (OR = 2.96 (CI 95% 1.59–5.50), p-value = 6.37 × 10−4)." (PMID 35884425, 2022). "In a recent study, PARP inhibition in BRCA1/2-negative breast cancer orchestrated a tumor-supporting microenvironment by inactivating PARP-2." (PMID 33923319, 2021). "Although PARP2 expression was strongly upregulated in all HNSCC tumor cell lines as compared to hTERT-immortalized OKF 6 cells, particularly high levels were observed in UPCISCC 040 and Cal 27 cells." (PMID 34911941, 2021). "Of note, we have previously demonstrated that dual deficiency for PARP-1 and PARP-2 in T cells results in a significant decrease of both CD4 and CD8 peripheral T cells and consequently impairs the T cell response to tumours." (PMID 34885119, 2021).
tumor (continued). "Enhanced tumour growth inhibition was also demonstrated with combined PARP2 silencing and IR treatment in HCC xenografts, when compared to IR alone." (PMID 34440228, 2021). "Overall, the presence of PARP-1 and PARP-2 in the tumor microenvironment appears to limit anticancer immunity and support tumor growth." (PMID 33923319, 2021). "According to research, PARP2 inhibitors can not only inhibite the repair of tumor cell DNA damage and promote tumor cell apoptosis as a single agent, but also enhance the efficacy of radiotherapy and chemotherapy with alkylating agents and platinum drugs." (PMID 33486472, 2021). "Selective PARP-1 inhibitors can not only be used as radiotherapy and chemotherapy sensitizers to enhance anti-tumor efficacy, but also would mitigate toxicities arising from cross-inhibition of PARP-2." (PMID 32373627, 2020). "We also tested the correlation of expression PARP2 with survival and tumour stages and found a positive correlation in only 2 datasets with lower effect respect to PARP1." (PMID 32103589, 2020). "PARP inhibition capitalises on the increased expression of PARP-1 and PARP-2 in a variety of tumours." (PMID 29527010, 2018). "For example, we showed that whereas both PARP1 and PARP2 co-express with cell cycle genes in tumor samples consistent with their known roles in DNA repair, only PARP2 strongly co-expresses with many C2H2-type zinc finger genes in normal tissues." (PMID 29259170, 2017). "This difference between PARP2 co-expressing genes in tumor samples and in normal samples is consistently observed over multiple TCGA cohorts." (PMID 29259170, 2017). "In the first example, we examined the difference in co-expressing genes for Poly (ADP-ribose) polymerase-2 (PARP2) in tumor tissues vs. normal tissues." (PMID 29259170, 2017). "The overexpression of miR-149 or the inhibition of PARP-2 expression can inhibit tumor growth, which is more effective in the sensitization of animals with HCC xenografts to chemotherapy and radiotherapy." (PMID 28045918, 2017). "Only two of the top 100 PARP2 co-expressing genes in BRCA normal samples belong to the “REACTOME_CELL_CYCLE” gene set, while close to half of the top 100 PARP2 co-expressing genes in BRCA tumor samples called by GRACE belong to this gene set." (PMID 29259170, 2017). "As a PARP inhibitor, olaparib can promote tumor cell apoptosis by inhibiting PARP2." (PMID 41123010, 2026). "The development of highly specificPARP-1 inhibitors not only meets the therapeutic needs of tumor treatmentbut also has the potential to minimize the adverse effects associatedwith nonselective PARP-2 inhibition." (PMID 39346823, 2024). "In breast cancer mouse models, PARP-2 deficiency did not affect tumor growth rate, but was associated with delayed tumor onset and a significant reduction in lung metastasis." (PMID 39201718, 2024). "[123I]CC1 also induced increased expression of PARP1 and PARP2 in tumor cells in vitro." (PMID 37770109, 2023). "Both PARP-1 and PARP-2 are the major pathways for DNA repair in tumor cells." (PMID 37165402, 2023). "PARP-1 and PARP-2 play a critical role in DNA repair, but they may also promote carcinogenesis and tumor progression in tissues." (PMID 36768904, 2023). "However, PARP2 contributes to tumour aggressiveness by regulating several cellular functions, including the glycolytic rate." (PMID 36600265, 2023). "The TCGA portal revealed that tumor tissues had higher PARP-2 expression than normal tissues." (PMID 35466317, 2022). "Although it seems clear that PARPi will not achieve the degree of inhibition that can be achieved by genetic deletion of PARP-1 and PARP-2, these inhibitors can affect the T cell compartment, which could compromise the T cell immune response to tumours." (PMID 34885119, 2021). "Increased IMCs in the marrow upon PARP2 deletion or inhibition may enhance bone metastasis through IMCs’ capabilities in supporting tumor cell growth and immunosuppression." (PMID 32221289, 2020).
tumor (continued). "Thus, any consideration of selective PARP2 inhibition in tumor cells and during metabolic unbalance will require better understanding of the exact mechanism of PARP2-dependent metabolic regulation." (PMID 31281570, 2019). "CCND1 and PARP2 are reported to be involved in tumor development and act as oncogenes." (PMID 31340767, 2019). "With the TCGA BRCA tumor samples, the top PARP2 co-expressing genes found by the standard method are mostly genes located near the PARP2 locus at chromosome 14q11.2, whereas the top co-expressing genes called by GRACE are from various chromosomes and many are involved in cell cycle processes." (PMID 29259170, 2017). "Selective PARP2 deficiency in the myeloid cell lineage did not affect tumor initiation." (PMID 40904702, 2025). "When developing a DNA damage response PET imaging agent and in order to completely understand its target engagement, we hypothesise that non-PARP1 and PARP2 effects should also be considered to understand how tumour uptake of a radiolabelled compound relates to PARP biology." (PMID 32342268, 2020). "Together, our data indicate that PARP2 deficiency suppresses tumor onset and lung metastasis yet increases bone metastasis without affecting primary tumor growth, suggesting that the microenvironment in bone is specifically responsible for the olaparib induction of bone metastasis." (PMID 32221289, 2020). "Preclinical evidence suggests that PARP1 inhibition mediates the tumor-targeted effects of PARP inhibitors, while PARP2 inhibition is primarily responsible for myelosuppression." (PMID 41145467, 2025). "Based on Gene Expression Profiling Interactive Analysis 2.0 (GEPIA2.0), PARP2 and SIRT6 were significantly upregulated in HCC tissues compared to those in non-tumor tissues." (PMID 39408693, 2024). "In HCC tissues, the mRNA and protein levels of PARP2 and SIRT6 were significantly higher than those of non-tumor tissues (p < 0.001)." (PMID 39408693, 2024). "Consistent with the results in GEPIA2.0, the mRNA expression of PARP2 and SIRT6 was significantly increased in HCC tissues compared to that in non-tumor tissues." (PMID 39408693, 2024). "PARP inhibitors (PARPi) exert their anti-tumor function by competitively displacing NAD + to bind to the catalytic site of PARP1 and PARP2, thus preventing DNA repair and thereby driving tumor cell death." (PMID 37662839, 2023). "According to data from databases (TCGA (The Human Protein Atlas)), PARP-2 is significantly correlated with HCC staging, tumor grade, and metastasis, and the high expression of PARP-2 presents worse prognostic indicators such as OS and PFS." (PMID 35466317, 2022). "Surprisingly, macrophages were redirected toward a pro-inflammatory, anti-tumor phenotype if we inhibit the PARP enzymatic activity in WT (PARP1 and PARP2 intact), PARP1-null (PARP2 intact), or PARP2-null (PARP1 intact) cells." (PMID 36223740, 2022). "A significant decline was observed in PARP-1 and PARP-2 protein expression levels in tumors of both LC and LC-COPD patients compared to the respective non-tumor samples in both groups." (PMID 33187221, 2020). "Supportive of compensatory roles, co-deletion of PARP1 and PARP2 results in embryonic lethality, however, PARP1−/− mice exhibit increased spontaneous tumor incidence suggesting PARP2 cannot fully compensate for PARP1 loss." (PMID 33005627, 2020). "Transcript levels of PARP1, PARP2 and PARP3 genes were evaluated in a panel of 17 RMS primary tumours (4 ARMSs and 13 ERMSs) by quantitative Real Time PCR (q-PCR) experiments." (PMID 30357520, 2019). "In the present study, we analysed the expression of PARP1, PARP2 and PARP3 genes in a panel of RMS primary tumours and cell lines, and evaluated the biological and molecular effects of PARP inhibition in RMS in vitro models by using Olaparib or AZD2461." (PMID 30357520, 2019).